KRT18 (keratin 18)
Diseases named in the same sentence as KRT18 in open-access papers (continued):
Sharing a sentence is not in itself a finding about the gene and the disease.
olfactory neuroblastoma (1 paper, 2022). An olfactory neuroblastoma arising in the paranasal sinus. "This predicts UCHL1 and KRT18 to be a potentially valuable marker combination for the differentiation of olfactory neuroblastomas and the SNUC classes." (PMID 36443295, 2022). "In contrast, cytokeratin 18 (KRT18) was strongly overexpressed in both NEC-like IDH2 and NEC-like SMARCA4/ARID1A cancers but not in olfactory neuroblastoma." (PMID 36443295, 2022).
orofacial cleft (1 paper, 2020). A disorder of facial skeleton that is characterized by cleft lip and/or cleft palate that result in feeding, speech and hearing problems caused by failures during development. "Next, we used the classifiers trained on zGPAEs, mPEAEs, and hOEAEs to predict which single nucleotide polymorphisms (SNPs) associated with risk for orofacial cleft near the KRT18 gene are most likely to disrupt an enhancer of the type upon which the classifier was trained." (PMID 32031521, 2020). "Finally, we used the classifier trained on zGPAEs to prioritize orofacial-cleft associated SNPs near KRT18, a gene expressed in periderm, for those that are likely to affect a periderm enhancer." (PMID 32031521, 2020). "We predict that differentiation human periderm is similarly controlled as genes encoding orthologs of these proteins are implicated in risk for orofacial clefting (e.g., GRHL3, KLF4, and KRT18)." (PMID 32031521, 2020).
osteonecrosis (1 paper, 2022). A none disease characterized by death of bone tissue due to a lack of blood supply. "Our finding suggests that KRT18 and PABPC3 may be implicated in MRONJ pathophysiology, and that they may be used as a therapeutic target in the treatment of osteonecrosis." (PMID 35456240, 2022).
paraganglioma (1 paper, 2020). A benign or malignant neoplasm arising from paraganglia located along the sympathetic or parasympathetic nerves. "Histologically, cauda equina paragangliomas show frequently gangliocytic differentiation and strong immunoreactivity to pan-cytokeratin and cytokeratin 18, which is not common in paragangliomas of other sites." (PMID 32926213, 2020).
pituitary tumor (1 paper, 2015). A benign or malignant neoplasm affecting the pituitary gland. "Based on GH immunoreactivity and keratin 18 accumulation, GC tumors are reminiscent of the human densely granulated subtype of human GH-producing pituitary tumors." (PMID 26549306, 2015).
progeria (1 paper, 2022). "Some genes that are downregulated during aging are upregulated in progeria patients (KRT8, KRT18, UCP2, ADAMTS15, ACTN4P1) while others (ACKR4) are upregulated in nonagenarians but downregulated in children suffering from HGPS." (PMID 36289702, 2022). "If KRT18 expression in fibroblasts is similar to other tissues, this finding might indicate that the nonagenarian fibroblast donors were of extremely good health or that progeria severely affects the skin, which corresponds to skin problems being among the typical progeria symptoms." (PMID 36289702, 2022).
renal fibrosis (1 paper, 2021). A final common manifestation of a wide variety of chronic kidney diseases characterized by glomerulosclerosis and tubulointerstitial fibrosis. "The aim of the study was to investigate the predictive value of urinary endoglin, periostin, cytokeratin-18, and transforming growth factor-β1 (TGF-β1) for assessing the severity of renal fibrosis in 81 children with CON and 60 controls." (PMID 34768419, 2021).
rotator cuff tear (1 paper, 2018). "In the present study, a rapid increase in Krt18 expression was found during the acute phase after inducing the rotator cuff tear." (PMID 30671462, 2018).
skin cutaneous melanoma (1 paper, 2023). "Notably, KRT18 was under-expressed in skin cutaneous melanoma relative to normal tissue." (PMID 36949761, 2023).
teratocarcinoma (1 paper, 2016). A germ cell tumor characterized by the presence of an embryonal carcinoma component and a teratoma component. "BYSL, together with keratin 18 are thought to be involved in teratocarcinoma." (PMID 27955658, 2016).
Testicular atrophy (1 paper, 2017). Wasting (atrophy) of the testicle (the male gonad) manifested by a decrease in size and potentially by a loss of fertility. "It is exactly such azoospermic men with mixed testicular atrophy who show Sertoli cell immaturity demonstrated by expression of antimüllerian hormone (AMH) and cytokeratin‐18 (CK‐18) in their adult Sertoli cells." (PMID 28061524, 2017).
urinary tract infection (1 paper, 2024). "In the control group, the majority of the top 20 DEGs were associated with the epithelial cells, including epithelial barrier‐related genes (CLDN4, KRT19, and KRT18), and SLPI, a key gene reported to be localized to bladder epithelial cells and protect against urinary tract infection in mouse model." (PMID 38414668, 2024).
tumor (349 papers, 2005 to 2026). "Recently, keratin 18 (KRT18), a cytoskeletal protein that is upregulated in most types of tumors, has been associated with the clinical stage, cancer progression, deep tumor invasion, metastasis, and poor survival in NSCLC patients." (PMID 35745691, 2022). "KRT8 and KRT18 were highly expressed in Mel106, and they were extensively used as diagnostic tumor markers." (PMID 35646893, 2022). "Meanwhile, we observed high KRT18 expression was associated with advanced clinical stage, deep tumor invasion, lymph node metastasis, distant metastasis, poor differentiation and unfavorable prognosis in CRC patients." (PMID 31345960, 2019). "It is suggested that the lower abundance in GII, a group with higher-grade neoplasms, may be related to an aberrant methylation of the KRT18 gene, thus causing silencing of this gene and lower expression of the protein in this group." (PMID 39057100, 2024). "To uncover the KRT18-associated ASEs in GC samples, we selected 50 GC samples, including 25 showing top high KRT18 expression (high group) and 25 showing bottom low (low group) from the 130 tumor tissue samples." (PMID 34290732, 2021). "In addition to cytomorphological analysis, gene expression of tumor associated genes (Cytokeratin-18, Cytokeratin-19, Cytokeratin-20, Cytokeratin-7, EPCAM, MUC1, HER2, EGFR) and of leukocyte markers (e.g. CD45, CD68) was tested in enriched CTC fractions." (PMID 25862542, 2016). "Areas consisting of small tumor cells mimicking ductular epithelium with hyperchromatic nuclei, high nuclear/cytoplasmic ratio and focal solid arrangement with nuclear crowding were also present in most tumors associated with Krt18-deficient mice." (PMID 27689336, 2016). "Since some Krt18-deficient mice showed chromosomal instability already at the age of 12 months in the tumor-free liver, keratin-related chromosomal instability seems to precede tumor development, and therefore might be a causal factor rather than a secondary event." (PMID 27689336, 2016). "This network suggests that intense epithelial-T cell cross-talk serves as a central communication hub driving hybrid (CD45+/KRT18+, KP_Pos) cell formation within the tumor microenvironment." (PMID 41355965, 2026). "The M30 neoepitope is a specific fragment of cytokeratin 18 (CK18) exposed during early apoptosis, which serves as a valuable biomarker for detecting apoptotic epithelial cells, including circulating tumor cells (CTCs)." (PMID 40076201, 2025). "In the CD45− population, clusters 0 and 1 were identified as major tumor clusters exhibiting high expression levels of epithelial cell markers (Krt8, Krt18, Krt19)." (PMID 40568084, 2025). "Cell clusters obtained were characterized based on their gene expression profile and identified as B16F10 tumor cells (Pmel, Mlana), mT4 tumor cells (Krt18, Krt19), and fibroblasts (Col1a1, Dcn)." (PMID 38987547, 2024). "we screened by ROC curves that the key regulatory gene of TEXRS, KRT18 (Keratin 18), is thought to be overexpressed in most types of human tumor and correlated with clinical progression and prognosis 55-57." (PMID 38495503, 2024). "Western blotting and the TUNEL assay are frequently utilized methods to identify cleaved caspases and fragmented DNA in tissue samples, showing presence of Serum M30, a caspase 3-cleaved cytokeratin 18, in patients with successful tumor responses." (PMID 39650649, 2024). "KRT18 gene is overexpressed in human cancer and positively correlated with tumor invasion/metastasis." (PMID 37439806, 2024). "Single-cell analysis revealed high expression of SPHK1 in tumor cells (SOX2, KRT18) and cancer-associated fibroblasts (COL1A2 and MMP2) and low expression in cancer stem cells (PROM1)." (PMID 39629135, 2024). "KRT18 has been suggested to be overexpressed in most types of human tumor, which is correlated with the malignant status and acts as an oncogene in colorectal cancer." (PMID 38213729, 2024).
tumor (continued). "Serum M30, a form of cleaved cytokeratin 18 by caspase 3, is detected in patients with tumor response to treatment, signifying cell death." (PMID 39650649, 2024). "To focus on TNBC cell populations within the VMT, we integrated the MDA-MB-231 VMT and HCC1599 VMT datasets and subset the tumor cells from the EPCAM+ or KRT18+ clusters in the individual datasets for further investigation." (PMID 38183074, 2024). "The results showed that METTL7A and PRKCH expression was significantly up-regulated in normal cell lines, while KRT18 expression was significantly up-regulated in tumor cell lines." (PMID 38495503, 2024). "Compared with normal tissues, IGFBP7, LBH and TFPI are low expressed in tumor tissues (P < 0.05), while KRT18, UBE2C and UBE2S were highly expressed in tumor tissues (P < 0.05)." (PMID 38077434, 2023). "Clusters 2, 6, and 11 expressed Keratin genes (Krt7, Krt8, and Krt18), suggesting their potential tumor origin." (PMID 37055410, 2023). "On the other hand, the epithelial cell markers Krt18 and Ocln were highly expressed in ascitic vs. omental tumor cells." (PMID 37095087, 2023). "Organoid cells were identified by the expression of the tumor markers KRT18 and KRT19 whereas CAFs were characterized by DCN and LUM expression." (PMID 36273171, 2022). "Another evidence of a possible direct effect of H89 on cancer cells is its ability to reduce the transcripts of certain tumor markers, such as keratin 18 (Krt18) and atypical cadherin (FAT2)." (PMID 35572581, 2022). "Tumor cells were identified by the formation of a cluster distinct from other cell types in PBMCs and the expression of epithelial markers such as KRT18." (PMID 35953080, 2022). "Immunohistochemical analyses of 35 CRC patients further revealed a preferential accumulation of neutrophils at sites of apoptotic tumour cells defined by the expression of epithelial cell-specific caspase-cleaved cytokeratin-18." (PMID 35121727, 2022). "HSPB1 and KRT18 were the tumor marker genes investigated, and patients were classified into PD-L1low and PD-L1high groups based on the relative expression of CD274 (Cutoff = 0.003)." (PMID 33754038, 2021). "Using ROC analysis in tumours defined by cytokeratin 18 expression (n = 101), low expression of E‐cadherin was the most sensitive and specific feature of SGST (AUC = 0.97, P < .0001) followed by SSTR2A (AUC = 0.82, P < .0001) and SSTR3 (AUC = 0.72, P = .0001)." (PMID 33491286, 2021). "By analyzing CTCs, we uncovered a positive correlation between CTCs expressing EMT markers and the epithelial marker KRT18 and the ability of the respective primary tumor to grow in mice." (PMID 34070013, 2021). "Among the staged 415 tumor tissue samples according to the standard of National Comprehensive Cancer Network stage, the expression of KRT18 was significantly up-regulated in most tumor stages, more pronouncedly in late stages." (PMID 34290732, 2021). "A cluster of cells was annotated as Krt18− tumor-like cells, with an expression profile similar to that of Krt18+ cells but with low Krt18 expression." (PMID 34373258, 2021). "Cytokeratin 18 (CK18) is a member of the family of type I keratins and is a component of the intermediate filament (IF) of epithelial cells and various tumor cells." (PMID 34521905, 2021). "Another sign of tumor cells undergoing apoptosis is the increase of caspase-cleaved cytokeratin 18 fragments (M30 antigen)." (PMID 32290637, 2020). "The relatively higher serum KRT18 levels in ESCC patients as compared to normal subjects were correlated with tumor progression." (PMID 32509787, 2020). "We chose one patient case LEG32 to conduct experiment because KRT18 was highly expressed in LEG32 tumor tissues." (PMID 32509787, 2020).
tumor (continued). "While only keratin 18 correlated with the tumor load at baseline, we found several individual markers correlating with the tumor response to treatment for each of the three time points of blood draws." (PMID 32290637, 2020). "Other noteworthy genes included DSPP, PER3, MTCH2, and KRT18, all have been reported with important roles in tumor formation and development." (PMID 32231683, 2020). "Xanthohumol remarkably suppressed the expression of both Ki67 and KRT18 protein in tumor tissues isolated from xanthohumol-treated group as compared to vehicle- treated group." (PMID 32509787, 2020). "Western blotting showed that honokiol treatment significantly decreased KRT18 protein level in tumor tissues." (PMID 33330500, 2020). "Then we examined the expression of Ki67 and KRT18 in xenograft tumor sections using the IHC analysis." (PMID 32509787, 2020). "To evaluate the expression of KRT18 in ESCC tissues, we checked the expression of KRT18 in an ESCC tumor microarray that included 37 pairs of adjacent tissues and cancer tissues and 40 more cancer tissues." (PMID 32509787, 2020). "In conclusion, KRT18 is overexpressed in CRC tissues and cell lines, and associated with tumor progression and overall survival." (PMID 31345960, 2019). "These greatly promoted tumor masses comprised not only cytokeratin-18 (CK18)-expressing Panc 02 cells and infiltrating α-SMA+ stromal cells, but also EndoMT cells that highly expressed α-SMA and CD31, confirming the participation of EndoMT cells in the tumors." (PMID 31847880, 2019). "Moderately-responding AMEs showed similar staining to naïve AMEs, with the exception of KRT18 staining which was present in less than 1% of tumour cells (compared to 20–45% positive cells in naïve tumours; n = 8)." (PMID 31080552, 2019). "Some relapsed MSCCs contained small regions with histopathological features that resembled AC(NST) or AME, contributing to the increased KRT18-positivity in these tumours, but some spindle cells also showed KRT18 staining." (PMID 31080552, 2019). "A significant increase in Krt18 expression was observed in −E2 D2.0R-inoculated mice compared to −E2 non-tumor-inoculated (naïve) mice." (PMID 30250146, 2018). "The surface area of cytokeratin-18 (KRT18)-positive tumor cells steadily increased upon culture, thereby representing an increase in viable tumor cells during ex vivo culture." (PMID 30333957, 2018). "Immunofluorescent and morphological analyses revealed degradation of KRT18 in the cancer cells indicative of decreased tumor cell viability and induction of cancer cell death." (PMID 30333957, 2018). "aCGH analysis of tumors revealed chromosomal aberrations in Krt18−/− liver tumors, affecting loci of oncogenes and tumor suppressor genes." (PMID 27689336, 2016). "K19-positive tumor cells were also present in the majority of tumors arising in Krt18+/− and wt mouse livers." (PMID 27689336, 2016). "The number of MDB-containing tumor cells, usually focally concentrated, was increased in Krt18+/− and Krt18−/− mice." (PMID 27689336, 2016). "It is noteworthy, however, that in some Krt18−/− liver tumors K8 immunoreactivity was noted in disseminated polygonal tumor cells or small cell groups (5–20 cells), sometimes in trabecular arrangement or in strands, whereas the small cells were negative." (PMID 27689336, 2016). "Apoptosis was measured for 57 patients (89.1%; 9 time points per patient) by detection of a tumor-specific neoepitope of cytokeratin 18 (M30) created during apoptotic cleavage." (PMID 25533314, 2015). "Among the proteins enriched in large EVs, cytokeratin 18 (CK18) emerged as a potential marker for tumor-derived EVs in tissues and in plasma." (PMID 25857301, 2015). "We first identified that OC inhibits tumor cell metastasis by up-regulating keratin 18 using proteomics analysis." (PMID 25973684, 2015).